ALB (albumin)
Diseases named in the same sentence as ALB in open-access papers (continued):
Sharing a sentence is not in itself a finding about the gene and the disease.
tumor (continued). "Patients with low CALLY scores were significantly more likely to have elevated CRP (p < 0.001), lower albumin (p < 0.001), reduced lymphocyte counts (p < 0.001), and higher tumor markers (CEA and CA19-9, both p < 0.001 and p = 0.001, respectively)." (PMID 41517561, 2025). "This retrospective cohort study revealed that PG-SGA score, previous abdominal surgery, operation time, advanced tumor stage, and albumin and hemoglobin levels were independent predictors of PPOI." (PMID 40271430, 2025). "By examining the mutated genes, we found that tumor cells progressively acquired non-synonymous mutations in genes such as KTN1, ALB, APOB, CDK11A, and CDK11B." (PMID 41373592, 2025). "Albumin nanoparticles coated with sugar wraps target tumor cells, enhancing shikonin uptake and reducing metabolic activity." (PMID 41272362, 2025). "In targeted drug delivery applications, albumin takes advantage of the enhanced permeability and retention (EPR) effect observed in tumor tissues, allowing for passive accumulation of albumin-bound drugs at cancer sites." (PMID 40699702, 2025). "Among systemic inflammatory markers and blood cell counts, serum albumin levels inversely correlated with TIMP1 histoscores in both tumor and stromal cells (p < 0.001 for both)." (PMID 39789100, 2025). "Among them, BCLC staging, tumor number, distant metastasis, ascites, age ≥60, aspartate aminotransferase ≥40 ug/L, albumin <35 g/L, alkaline phosphatase ≥125 ug/L were all identified as characteristic factors." (PMID 39372198, 2024). "The only indicator that correlated significantly with a more frequent tumor dissemination on all three levels was pre-albumin < 20 mg/L." (PMID 38339372, 2024). "The decrease of albumin will lead to the failure of antioxidants to repair, and then promote the progression of tumor." (PMID 38579053, 2024). "Serum albumin (odds ratio (OR) 0.005, p = 0.006), PT% (OR 0.80, p = 0.004), and largest tumor diameter (OR 1.99, p = 0.006) were significant predictors." (PMID 39487694, 2024). "Both laboratory markers can be altered in patients with a malignant tumor due to a tumor-induced pro-inflammatory state (albumin) and the direct effects of invasive tumor growth itself (alkaline phosphatase)." (PMID 39596952, 2024). "We can assess the patient’s tumor burden and disease progression based on biochemical indicators (e.g., hemoglobin, serum calcium, β2-microglobulin(β2M), serum albumin, lactate dehydrogenase(LDH)) to determine the stage of the disease." (PMID 38562177, 2024). "PNI, calculated from serum albumin content and total lymphocyte count, reflects the nutritional status and immunity of tumor patients." (PMID 39403382, 2024). "We set out to develop a novel strategy to deliver fully functional IL-12 and other biologics to the TME by binding albumin, taking advantage of its ability to be concentrated and retained in the tumor." (PMID 39697343, 2024). "Albumin has a long half-life and, by binding to the albumin-specific receptor, nab-paclitaxel can accumulate in the tumor more effectively than paclitaxel by an enhanced permeability and retention (EPR) effect." (PMID 39335147, 2024). "Albumin conjugationin RABiT thus promoted selective and efficient tumor delivery whileminimizing undesired off-target activation." (PMID 39071065, 2024). "Patient characteristics, including age, sex, body mass index, serum albumin, C-reactive protein, tumor markers, prognostic nutritional index (PNI), modified Glasgow prognostic score (mGPS), and geriatric nutritional risk index (GNRI), were also analyzed." (PMID 39410049, 2024). "Delivery systems based on albumin nanoparticles (NPs) have recently garnered substantial interest in anti-tumor drug development." (PMID 39070787, 2024). "Multivariable analysis showed that serum albumin ≤ 3.8 g/dL, PT ≤ 80%, and largest tumor diameter ≥ 3.8 cm were predictors of deterioration of the Child‐Pugh class." (PMID 39487694, 2024).
tumor (continued). "Desai N was involved in the development and application of Abraxane® and Fyarro® and is a pioneer in the application of albumin-bound anti-tumor drugs to clinical practice." (PMID 39070787, 2024). "In this systematic review, serum CA19-9, bilirubin, albumin, CEA, NLR, PLR, and tumour MMP9 were the only biomarkers associated with prognosis for pCCA resected with curative intent in at least two separate studies." (PMID 38398089, 2024). "A combination of serum albumin ≤ 3.8 g/dL, PT ≤ 80%, and largest tumor diameter ≥ 3.8 cm can predict the immediate deterioration of the Child‐Pugh classification from A to B following TACE." (PMID 39487694, 2024). "This led to apparently enhanced internalization of the albumin–drug–carriercomplex into Her2(+) cells in a tumor implant in mice (inoculatedwith Her2(+) BT-474 human breast cancer cells)." (PMID 38231473, 2024). "Such homogenates or activated MMPs were incubated with serum albumin or IgG in order to study if tumor tissue or MMPs have the capacity to generate active fragments from these proteins." (PMID 39518029, 2024). "Hepatocytes were widely distributed in the tissue, scattered in both the “normal zone” and “tumor zone”, with a higher quantity in the “normal zone” than in the “tumor zone”, corresponding to the distribution range of the marker gene ALB." (PMID 38672453, 2024). "The chi-square test showed that serum albumin concentration, histological grading of the tumor, HER2 status and changes in tumor blood supply after two therapy cycles were significantly associated with the pcr rate in bc patients after NACT." (PMID 39013971, 2024). "Prognostic factor: Body mass index, albumin, platelet, leukocyte, tumor differentiation, and the status of the pelvic LN." (PMID 39534844, 2024). "This is the first FDA-approved drug for treating advanced malignant PEComa in adults and the second anti-tumor product developed and marketed based on albumin technology." (PMID 39070787, 2024). "This established model comprises eight indices for clinical application: BCLC staging, tumor number, presence of distant metastasis, ascites, age ≥60 years, aspartate aminotransferase ≥40 ug/L, albumin <35 g/L, and alkaline phosphatase ≥125 ug/L." (PMID 39372198, 2024). "A systematic evaluation of 29 epidemiological studies by Digant showed that serum albumin level before treatment was an independent predictor of survival of tumor patients and had important significance for evaluating the prognosis of tumor patients." (PMID 39010005, 2024). "Here, divalent lipid-conjugated siRNAs are optimized for in situ binding to albumin to improve pharmacokinetics and tumor delivery." (PMID 38383524, 2024). "Another effective strategy that exploits the affinity of albumin for cyanine dyes in tumor targeting is based on the preparation of albumin nanoparticles." (PMID 39138299, 2024). "Taken together, these data demonstrate that nanobody albumin hitchhiking can increase tumor accumulation to allow for endocytosis of cargo by multiple tumor-associated cell types." (PMID 38766114, 2024). "Abraxane NPs (albumin-based NP formulation of paclitaxel) conjugated with different tumor-homing peptides that selectively recognize tumor blood vessels or tumor lymphatics were tested for targeting cancer cells in mice with breast tumors." (PMID 39125610, 2024). "Nanomaterials can be coated with other biomolecules, such as albumin (Alb), to facilitate high accumulation in tumor sites and enable low-dose radiation to take effect." (PMID 39045421, 2024). "In further experiments, we investigated the impact of albumin and Rituximab on NK–tumor cell conjugation either in the presence or in the absence of Cetuximab." (PMID 38646521, 2024). "Incorporating an albumin strategy to help target and retain IL-12 in the tumor tissue has the potential to be more effective than injecting recombinant IL-12 alone." (PMID 39697343, 2024).
tumor (continued). "We conducted Kaplan-Meier (K-M) survival analyses for the most influential variables: eGFR, Albumin, and Tumor Size." (PMID 38519947, 2024). "PNS was milder (with higher serum albumin and lower proteinuria levels) in the group in which NS was detected first than in the group in which the tumor was detected first and the group in which the two diseases were detected simultaneously." (PMID 38965515, 2024). "Dp_ROI_Low, tumor size, serum albumin, platelet count, and lymphocyte count were independently related to high WHO/ISUP nuclear grade in the training set." (PMID 39695867, 2024). "HCC patients in LFIS Group 3 and Group 4 had worse liver functional reserve (higher Child–Pugh scores, ALT, AST, GGT, ALP, LDH, TBIL, and lower ALB levels) and had larger tumor diameters, more macrovascular invasion and higher AFP level." (PMID 38834790, 2024). "Studies have indicated that albumin nanoparticles can accumulate in tumor tissues through passive and active targeting mechanisms, underscoring their therapeutic potential in cancer treatment." (PMID 39272576, 2024). "There was a significant association between the risk of grade 3-5 postoperative complications and age (P=0.023), ASA score (P=0.001), preoperative albumin levels (P<0.001), and tumour location (P=0.002)." (PMID 38577607, 2024). "For patients with known preoperative hypoproteinemia, we should actively improve their nutritional status or perform perioperative intravenous infusion of human albumin before performing radical tumor resection." (PMID 39868370, 2024). "Specifically, eGFR was divided into higher and lower groups using a threshold of 86.2, Albumin using 4.35, and Tumor Size using 45.5." (PMID 38519947, 2024). "Research has demonstrated the efficacy of tumor-targeted multifunctional albumin-based nanoparticles in treating U87 human GBM cells both in vitro and in vivo." (PMID 39272576, 2024). "It is well-known that albumin can accumulate selectively into the tumor interstitium, which is the enhanced permeation and retention (EPR) effect." (PMID 38542401, 2024). "There was a weak inverse correlation between tumor size and albumin (r = −0.026, p = 0.018) and ALT (r = −0.23, p = 0.036) levels after surgery in patients on the hospital-based diet." (PMID 38610609, 2024). "Albumin nanoparticles bind to glycoprotein 60 receptors expressed on vascular endothelial cells of the tumours." (PMID 39771562, 2024). "Although nutritional status is typically unaffected before or in the early stage of tumor incidence, certain studies have revealed that albumin declines before or in the early stage of tumor occurrence." (PMID 38384810, 2024). "Serum albumin ≤ 3.8 g/dL, PT ≤ 80%, and largest tumor diameter ≥ 3.8 cm were three independent predictors of Child‐Pugh class deterioration." (PMID 39487694, 2024). "This has laid a solid theoretical foundation for basic research and the rational development and utilization of albumin NPs as targeted carriers of anti-tumor drugs." (PMID 39070787, 2024). "The independent risk factors for early recurrence in HBV-related HCC patients after surgery were tumor diameter > 5 cm, albumin level < 35 g/L, and MVI." (PMID 39286273, 2024). "In this study, clinical parameters included LSWV, DPV, ALT, AST, ALP, γ-GGT, ALB, PT, and tumor volume." (PMID 38549933, 2024). "A nano-drug delivery system using targeting ligand-modified albumin demonstrated enhanced antitumor efficacy against tumor growth and lung metastasis in mice, underscoring the potential of inhaled protein-based formulations for effective cancer treatment." (PMID 39204164, 2024). "Nanoparticles composed of CS, doxorubicin, and bovine serum albumin targeting CD44 were reported to suppress 4T1 tumor growth." (PMID 38783892, 2024). "After that, the tumor spheres were incubated with FITC‐conjugated bovine serum albumin (FITC‐BSA, 1 mg mL−1) to evaluate drug penetration with a fluorescence microscope." (PMID 38417121, 2024).
tumor (continued). "This biological mechanism facilitates the tumor's ability to satisfy its elevated metabolic demands for rapid proliferation, leading to a decline in serum albumin concentrations." (PMID 38169970, 2024). "On November 17, 2020, immunotherapy was combined with chemotherapy (Sintilimab + Albumin-bound paclitaxel + Cisplatin), and a CT scan conducted three months later revealed significant tumor regression with a favorable therapeutic effect." (PMID 38357203, 2024). "During Phase 2 (2008–2014), Abraxane® achieved great success and contributed to the growing body of research on albumin NPs as anti-tumor drug carriers." (PMID 39070787, 2024). "Serum albumin, bilirubin, PT%, ascites, and largest tumor diameter were selected for multivariable logistic regression analysis." (PMID 39487694, 2024). "Tumor differentiation, albumin, and ABO type significantly revealed independent influence on glycan-specific lectins, such as RCA-I (p = 0.024), VVL (p = 0.024), and Con A (p = 0.026) in the postoperative serum." (PMID 39382267, 2024). "We developed a new prognostic model, called the TACE-prognostic (TP) score, based on tumor burden (sum of the largest tumor diameter and tumor number), alpha-fetoprotein, and Albumin-Bilirubin grade." (PMID 38606106, 2024). "Ling-Yu Chen and his team developed albumin-based cisplatin-gold nanoparticles (Au-cisplatin NPs), demonstrating remarkable superiority in tumor control and anti-tumor immunity when combined with radiotherapy." (PMID 38646428, 2024). "In the present study, binding of [67Cu]Cu‐NODAGA-cLAB4-TATE to albumin improved the tumor-to-kidney dose ratio compared to treatment with [67Cu]Cu‐NODAGA-TATE." (PMID 39310112, 2024). "The PhAα, NRS-2002, ECM/BCM index, NRI, albumin, and prealbumin showed a significant correlation with postoperative residual tumor." (PMID 38339372, 2024). "In accordance with their nuclearaccumulation, the Cu(II) complexes are able to cleave pDNA and interactwith bovine serum albumin, which is a good indication of their abilityfor internalization and transport toward tumor cells." (PMID 38518246, 2024). "Compared with the unmodified albumin NPs, surface-modified albumin NPs exhibit a more specific targeting effect and further increase the accumulation of NPs at the tumor site." (PMID 39070787, 2024). "As for CRP/albumin, it positioned itself at a certain distance from the previous ones and at the same level as other variables, such as those dependent on the tumor." (PMID 39199720, 2024). "Albumin is the most abundant transport protein in blood and it transports a myriad of anti-tumor proteins to the tumor site." (PMID 38730986, 2024). "This formulation, also known as Paclitaxel for Injection (Albumin Bound), has demonstrated the ability to enhance the anti-tumor effectiveness of PTX while simultaneously reducing the associated side effects." (PMID 38562665, 2024). "Nano-albumin-bound (nab)-paclitaxel is an innovative drug that depletes tumor stroma through interaction between albumin and secreted acidic protein rich in cysteine." (PMID 38378604, 2024). "The nomogram, integrating the albumin/globulin ratio, gender, tumor number, and size, showcased robust predictive performance." (PMID 38799452, 2024). "Patients who had the following factors including male, the number of comorbidities ≥2, postoperative serum albumin <35 g/L, tumor location was esophagogastric junction, duration of operation ≥260 min were more likely to develop EJAL than those who had not." (PMID 39669366, 2024). "As a nanocarrier, we employed a 67 kDa-sized poly(N-(2-hydroxypropyl) methacrylamide) (PHPMA) polymer, as this prototypic albumin-sized macromolecule has consistently provided us with high levels of tumour accumulation in a variety of models." (PMID 38589466, 2024). "Following combined treatment with albumin-bound paclitaxel, carboplatin, bevacizumab, and cadonilimab, the patient's tumor was effectively controlled." (PMID 38706596, 2024).
tumor (continued). "Multivariate analysis revealed that age, the albumin–bilirubin (ALBI) grade, and Child–Pugh class B status were independent factors associated with tumor recurrence." (PMID 39766066, 2024). "The research indicates a growing trend in the use of albumin NPs as anti-tumor drug carriers over the past 20 years, with a notable increase in publications after 2015 suggesting a continued interest in this topic." (PMID 39070787, 2024). "The innate tumor-homing ability of albumin is insufficient to concentrate the drug effectively at the tumor site, which can result in diminished therapeutic efficacy." (PMID 39479443, 2024). "For example, albumin-bound nanoparticle (nab) paclitaxel exhibits enhanced paclitaxel tissue distribution and tumor penetration, and has become the most successful anti-tumor nanomedicine used in the clinic." (PMID 38589859, 2024). "The aim of this work was to design and evaluate albumin-based nanoparticles, coated with dextran, as carriers for bevacizumab in order to promote its accumulation in the tumor and, thus, improve its antiangiogenic activity." (PMID 39455507, 2024). "Six parameters are considered in calculating the complication score, which represents the risk factors for complications: hemoglobin (Hb), preoperative serum albumin, tumor localization, EC (epidural catheter), use of opioids, and NPO (nil per os)." (PMID 39845228, 2024). "In this context, the initially higher tumor uptake appears to be surprising, considering that binding to albumin in the blood circulation lowers the actual concentration of the free radioligand." (PMID 39310112, 2024). "Among these indicators, albumin and hemoglobin levels reflect the nutritional and metabolic status of tumor patients." (PMID 39301556, 2024). "Studies have shown that albumin nanoparticles loaded with bevacizumab can selectively accumulate in tumor blood vessels, effectively inhibit tumor angiogenesis, improve tumor vascular function, and enhance the oxygenation status of tumor tissues." (PMID 39845318, 2024). "These scores use multiple parameters related to tumour burden (tumour size and number), liver function (albumin and bilirubin levels) and the clinical condition of the patient (ascites and encephalopathy)." (PMID 39061188, 2024). "This combination, melding albumin with AuNPs, amplifies the system's stability and selectivity, minimizes interaction with plasma proteins, and facilitates efficient targeting to tumor cells." (PMID 38164500, 2024). "Metabolism-related genes such as AHSG, ALB, and APOE gradually increased in expression during the mid-late stage of development, indicating their stronger association with abnormal tumor metabolism." (PMID 38230205, 2024). "The reduced glucose levels mediated by EcN facilitated the enhanced uptake of BAY-876 bound human serum albumin nanodrugs by CT26 tumor cells, thereby creating a more favorable condition for the therapeutic intervention to take effect." (PMID 39479443, 2024). "Previous studies suggested that the volume of HCC tumor is negatively correlated with the level of ALB." (PMID 39544939, 2024). "Due to the mechanically distorted and porous structure of the tumor vasculature, albumin (and also albumin-bound ligands) can leak into the interstitial space of the tumor but not the OAR." (PMID 38252191, 2024). "In summary, these mechanistic studies indicate that proteins like albumin are able to reduce cytotoxic NK cell activity and impair NK–tumor cell conjugation by inhibiting influx of calcium in NK cells." (PMID 38646521, 2024). "PEGylated bovine serum albumin-coated silver nanoparticles have revealed significant tumor accumulation, stability against degradation and hepatic clearance, leading to marked tumor growth inhibition upon local laser exposure." (PMID 38668189, 2024).